ABCG2 (ATP binding cassette subfamily G member 2 (JR blood group))
Diseases named in the same sentence as ABCG2 in open-access papers (continued):
Sharing a sentence is not in itself a finding about the gene and the disease.
gout (continued). "ATP-binding cassette transporter subfamily G member 2 (ABCG2) is located in a gout-susceptibility locus on chromosome 4q, which was identified by previous studies including genome-wide association studies of serum uric acid levels." (PMID 32180207, 2020). "ABCG2 rs10011796 displayed a similar pattern of association in Europeans as rs2231142, albeit with a weaker effect size (OR = 1.39, P = 3.5E− 11 for gout vs. HU, and OR = 1.18, P = 7.8E− 07 for HU vs. NU)." (PMID 32164793, 2020). "Mutations in these genes are associated with diseases, including cystic fibrosis (ABCC7/CFTR), Tangier disease (ABCA1/CERP), Dubin–Johnson syndrome [ABCC2/multidrug resistance‐associated protein (MRP2)] and gout [ABCG2/breast cancer resistance protein (BCRP)]." (PMID 33128234, 2020). "In humans, certain dysfunctional ABCG2 variants are associated with hyperuricemia and increased risk of gout, including the early onset of gout disease and expression of the severe tophaceous gout phenotype." (PMID 33330529, 2020). "Collectively, at ABCG2 at least, these findings emphasise the need to carefully account for ancestry in studies investigating the genetic causes of gout in the Polynesian populations of New Zealand." (PMID 32164793, 2020). "Particularly, individuals of European descent who carried ABCG2 variants had a significantly earlier onset of gout/hyperuricemia and the family history of gout was significantly more frequent among them." (PMID 33087043, 2020). "In conclusion, our study suggested that the ABCG2-rs2231142 SNP increased the risk of gout and serum urate in both Asians and Caucasians." (PMID 33087043, 2020). "The strength of association of ABCG2 rs2231142 with gout in the presence of HU in European was significantly different to SLC2A9 rs11942223 (ORrisk allele = 1.85 for rs2231142 compared to ORrisk allele = 1.37 for rs11942223, PHet = 2.1E− 03)." (PMID 32164793, 2020). "Recently it has been described that ABCG2 dysfunction is a strong independent risk factor for pediatric-onset hyperuricemia/gout." (PMID 31254042, 2020). "The pathophysiological nature of the common ABCG2 gout and hyperuricemia associated variant Q141K (rs2231142) remains undefined." (PMID 32488095, 2020). "For example, the mutational hot spot helix in ABCG2 carries the Q141K and R147W polymorphisms, both of which are linked to defective urate transport in gout owing to reduced stability of ABCG2." (PMID 33169382, 2020). "For SLC2A9 rs11942223, the T allele associated with gout in the presence of HU in European (OR = 1.37, P = 4.7E− 06), however significantly weaker than ABCG2 rs2231142 141K (PHet = 0.0023)." (PMID 32164793, 2020). "Regarding ABCG2, risk effects of rs2231142 were consistently found on gout, hyperuricemia and increased serum urate in Asians." (PMID 33087043, 2020). "In Europeans and Polynesians, the ABCG2 141K (T) allele was associated with gout using HU controls (OR = 1.85, P = 3.8E− 21 and ORmeta = 1.85, P = 1.3E− 03, respectively)." (PMID 32164793, 2020). "This region contains several important residues for ABCG2 folding and function, including the Q141K polymorphic site linked to gout." (PMID 33169382, 2020). "The 141K allele of ABCG2 associated with increased gout flare frequency in Polynesian (Pmeta = 2.5E− 03)." (PMID 32164793, 2020). "These variants tend, as does 141K, to reduce the urate transport ability of ABCG2; they associate with gout and, including 141K, associate with an earlier age-of-onset of gout." (PMID 32164793, 2020). "Severe impairment of ABCG2 function causes hyperuricemia and gout associated with excessive renal urate filtration (“renal uric acid overload”)." (PMID 33330529, 2020). "Common variants of the urate excretion transporter ABCG2 are known to significantly elevate gout/hyperuricemia susceptibility and are a major cause of early onset gout." (PMID 31975031, 2020).
gout (continued). "We report association of the ABCG2 rs2231142 141K (T) allele with gout in the presence of HU in European, Eastern and Western Polynesian sample sets." (PMID 32164793, 2020). "Our findings indicate epistasis between PKD2 and ABCG2 influence serum urate concentrations, hyperuricemia and gout risk, thus providing insight into the pathogenesis of gout." (PMID 32000861, 2020). "Dysfunctional variants of ATP-binding cassette transporter subfamily G member 2 (ABCG2), a urate transporter in the kidney and intestine, are the major causes of hyperuricemia and gout." (PMID 32180207, 2020). "We did observe an effect also for SLC2A9 rs11942223 in the gout vs HU comparison for Europeans (OR = 1.37 for risk allele); however, this was notably weaker than that for ABCG2 rs2231142 (OR = 1.85; PHet = 0.0023)." (PMID 32164793, 2020). "Deficiency in ABCG2 generates dysfunctional mitochondria and reduced copy number of mitochondrial DNA associates with increased risk of gout in NZ Polynesian." (PMID 32164793, 2020). "Even though serval GWAS studies found PKD2 variants associated with serum urate and gout, none variants in the PKD2 gene were independently associated with serum urate and gout conditional on the ABCG2 variants." (PMID 32000861, 2020). "An ABCG2 genotype combination (rs2231142-rs10011796) confers especially high risk for gout in Polynesian people with hyperuricaemia." (PMID 32164793, 2020). "PKD2 is located nearby ABCG2, which encodes a urate transporter that plays a certain role in serum urate concentrations and gout risk." (PMID 32000861, 2020). "ABCG2, which is reported to be associated with the onset of gout according to genetic analysis, has an important role in inflammation through inhibition of oxidative stress and NF-κB." (PMID 32180207, 2020). "This conclusion is also supported by other research groups, which have successively used HRM for association studies of ABCG2 polymorphisms with gout and Jr(a-) phenotype." (PMID 33003314, 2020). "The most updated review of ABCG2 included 12 individual studies, indicating that carrying the A allele of rs2231142 increased the risk of gout by about 1.8–2.3 times relative to the C allele in Asian and non-Asian populations." (PMID 33087043, 2020). "The minor allele frequency (MAF) of ABCG2 rs72552713 in the gout group was much higher than that in the control group, implying a correlation between this risk allele and disease susceptibility." (PMID 30621105, 2019). "In this work, we present the first study of ABCG2 allelic variants in a pediatric-onset hyperuricemia and gout cohort." (PMID 30894219, 2019). "Taken together, our data suggested that ABCG2 genetic variants have a strong impact on the progression of hyperuricemia and gout in pediatric-onset patients and imply the importance of ABCG2 genotyping for the screening of high-risk individuals." (PMID 30894219, 2019). "In the next decade, after identifying ABCG2 as a physiologically important urate transporter, a positive relationship between ABCG2 dysfunction and increased risk of human diseases, such as gout and hyperuricemia was revealed." (PMID 30890942, 2019). "The magnitude of effect of the ABCG2 variant appears to be greater in men than women for both serum urate and gout risk." (PMID 30626429, 2019).
gout (continued). "Our data show, for the first time, that ABCG2 dysfunction is a strong independent risk for pediatric-onset of hyperuricemia and gout." (PMID 30894219, 2019). "This study revealed that ABCG2 SNP rs2231142 was associated with gout renal comorbidities including nephrolithiasis and CKD." (PMID 31367212, 2019). "Among these exporter dysfunctions, ABCG2 is the most relevant genetic factor in the pathogenesis of hyperuricemia and gout patients based on genome-wide association study (GWAS)." (PMID 31491937, 2019). "Previous studies have suggested an association between hyperuricemia and gout susceptibility relative to dysfunctional ABCG2 variants, with rs2231142 (Q141K) being the most common." (PMID 30894219, 2019). "Accumulating evidence demonstrates that congenital dysfunction of ABCG2 is an important genetic risk factor in gout and hyperuricemia; recent studies suggest the clinical significance of both common and rare variants of ABCG2." (PMID 31003562, 2019). "Common genetic variants of the ABCG2 gene, such as C376T, have been strongly associated with gout risk in various populations." (PMID 30621105, 2019). "In a GWAS of clinically defined gout, the ABCG2 locus showed the most significant association with gout susceptibility." (PMID 30894219, 2019). "To understand of the relationship between these genes and gout we conducted a case-control association study of ABCG2 rs72552713, rs12505410 and SLC22A12 rs11231825, rs7932775 in the Vietnamese population." (PMID 30621105, 2019). "Unlike these reports, our study shows that the SLC2A9 variant exerts a greater risk of gout compared with the ABCG2 variant." (PMID 30626429, 2019). "Patients with dysfunctional variants in ABCG2 were identified to present symptoms onset 6.5 years earlier than those with the wild-type variant, indicating genetic effects of these variants on gout." (PMID 30621105, 2019). "In the present study, we employed an enlarged cohort of 250 patients with hyperuricemia or gout to determine non-synonymous allelic variants of ABCG2 related to the risk of such diseases." (PMID 31003562, 2019). "For ABCG2 rs72552713, the association of genotypes with gout was tested in only the dominant model because TT genotype was not present in the studied population." (PMID 30621105, 2019). "Previous candidate analyses and GWASs11,12,58 of clinically defined gout identified nonsynonymous variants of gout susceptibility genes such as ABCG2 (rs72552713, Q126X; rs2231142, Q141K) and GCKR (rs1260326, L446P)." (PMID 30993211, 2019). "This study identified a high frequency of ABCG2 variants, common and rare, in a cohort of pediatric-onset primary hyperuricemia and gout patients." (PMID 30894219, 2019). "Wherefore, this study explored into the association between ABCG2 SNP rs2231142 affecting common comorbidities and the therapeutic effect of allopurinol in Chinese Han male gout patients." (PMID 31367212, 2019). "We and others have performed GWASs of gout by comparing the genetic differences between gout cases and normouricaemia controls and have identified gout risk loci such as ABCG2 and SLC2A9: these are similar results to those from GWASs of SUA." (PMID 31289104, 2019). "For the examination of the effects of the ABCG2 rs2231142 genetic polymorphism on gout and its comorbidities, levels of serum uric acid and other biochemical results were compared among different genotype groups at baseline." (PMID 31367212, 2019). "ABCG2 also transports various endogenous substances, such as bile acid and uric acid, and it has been reported that the risk of gout is increased if excretion of uric acid by ABCG2 is inhibited." (PMID 31340525, 2019). "Our findings contribute to deepening the understanding of ABCG2-related gout/hyperuricemia risk and the biochemical characteristics of the ABCG2 protein." (PMID 31003562, 2019).
gout (continued). "One common ATP-binding cassette subfamily G member 2 (ABCG2) gene variant, which is encoded by the single nucleotide polymorphism (SNP) rs2231142, was identified to take an essential part in gouty arthritis." (PMID 31367212, 2019). "Previous studies have reported polymorphism in ABCG2 to be associated with gout in several populations, such as, European Americans, African Americans, Mexican Americans, Americans Indians, German, Japanese and Han Chinese9,10,23–25." (PMID 30899057, 2019). "Genotyping of ABCG2 is essential for risk estimation of gout/hyperuricemia in patients with very early-onset and/or a family history." (PMID 30894219, 2019). "Over the last two decades, genome-wide association studies and meta-analyses have identified several genes associated with gout susceptibility, including ATP-binding cassette subfamily G member 2 (ABCG2) and solute carrier family 22 member 12 (SLC22A12)." (PMID 30621105, 2019). "These different findings can partly be attributed to the population substructure and sample size considering that the majority of the GWAS with a strong association between ABCG2 and hyperuricemia/gout were conducted in European or Asian descent populations." (PMID 30894219, 2019). "According to the original genome-wide replication studies and association scans, common variants in ABCG2 (i.e. rs10011796 and rs2231142) demonstrated the strongest associations with gout." (PMID 31367212, 2019). "To this point, we recently identified ten non-synonymous variants of ABCG2, including two common variants and eight rare variants, using a cohort of 145 patients with gout in the Czech Republic." (PMID 31003562, 2019). "In summary, our findings will deepen our understanding of ABCG2-related gout/hyperuricemia risk as well as the biochemical characteristics of the ABCG2 protein." (PMID 31003562, 2019). "Consistent with previous reports, SLC2A9 and ABCG2 variants exerted the highest risk for gout among the whole group." (PMID 30626429, 2019). "These populations, with a specific distribution of dysfunctional ABCG2 variants, thus increase the risk of gout." (PMID 30894219, 2019). "In the present study, we explored the exonic non-synonymous variants of ABCG2 using a cohort of 250 individuals (68 primary hyperuricemia patients and 182 primary gout patients) recruited from a European descent population in the Czech Republic." (PMID 31003562, 2019). "In accordance with previous reports, we found a significant association between ABCG2 rs72552713 and an elevated risk of gout in the Vietnamese population." (PMID 30621105, 2019). "It was reported in previous literature that the function loss of ABCG2 caused by genetic mutation was closely related to gout and gouty arthritis." (PMID 31367212, 2019). "Nevertheless, this “Common Disease, Multiple Common and Rare variant” model for the association between ABCG2 and gout needs to be further validated, especially in other populations." (PMID 31003562, 2019). "ABCG2 is also known to be a major cause of gout and hyperuricemia that acts by decreasing urate excretion." (PMID 30189835, 2018). "Since the polymorphism rs2231142 in ABCG2 gene showed most significant association with gout or hyperuricemia, we displayed the LD according to different rs2231142 genotypes." (PMID 29453348, 2018). "We specifically examined gout patients in this regard because of a higher ABCG2 mutation rate expected in this disease." (PMID 29749379, 2018). "For GCKR and ABCG2, association with gout was observed for both the presence of at least one urate-raising allele as well as by number of urate-raising alleles." (PMID 29976226, 2018). "In summary, the known genetic associations at ABCG2 and SLC2A9 with serum urate and gout were replicated in CKD patients with higher effect sizes for ABCG2 in patients with CKD compared to individuals from the general population." (PMID 30181573, 2018).
gout (continued). "This latter role was emphasized by the GWAS studies showing the role of polymorphic variants of ABCG2 in gout formation." (PMID 29649238, 2018). "The urate-increasing GCKR and ABCG2 alleles were associated with gout (multivariate adjusted p < 5 × 10−8 for both), but the urate-increasing MLXIPL and CYP1A2 alleles were not." (PMID 29976226, 2018). "Since we found one heterozygous individual for this mutation among the gout patients and one among the healthy volunteer group, we screened the DNA samples of a larger cohort of healthy individuals for the prevalence of the ABCG2-M71V variant." (PMID 29749379, 2018). "The two lead SNPs rs2231142 and rs3114018 in ABCG2 on chromosome 4 was associated with hyperuricemia or gout." (PMID 29558500, 2018). "The five SNP-IV (excluding the ABCG2 SNP, which associates with uric acid) was inversely related to both gout risk and uric acid levels, supporting a causal relationship between coffee drinking and gout." (PMID 30241358, 2018). "Odds Ratios (OR) for the associations with gout from the GWAS of gout were 1.54 (95% CI: 1.34; 1.78) for ABCG2 rs2231142 and 0.77 (95% CI: 0.68; 0.86) for SLC2A9 rs13111638." (PMID 30181573, 2018). "The direct effect of the urate-associated ABCG2 SNP accounted for most of the total observed effect on gout risk, with a much smaller indirect effect mediated by coffee consumption (beta 0.848, SE 0.049 compared with beta 0.014, SE 0.03)." (PMID 29976226, 2018). "In mediation analysis, the direct effects of GCKR and ABCG2 accounted for most of the total effect on gout risk, with much smaller indirect effects mediated by coffee consumption." (PMID 29976226, 2018). "The aim of this study was to examine the role of SLC2A9 and ABCG2 variants in tophaceous disease in people with gout." (PMID 28270222, 2017). "To verify further the impact of polymorphisms in genes related to gout, we studied common genetic variability in ABCG2 using a case-control study to clarify the association between SNPs or haplotypes at ABCG2 with the risk of gout in a Chinese population." (PMID 28855613, 2017). "For example, two recent studies from northwest China21, 38 found a significant difference in mean serum urate levels between a novel SNP, rs3114018, in ABCG2 and gout risk, which is consistent with the findings of the present study." (PMID 28855613, 2017). "The key finding of this study is the ancestry-specific differences in the association between ABCG2 variants and tophaceous disease in people with gout." (PMID 28270222, 2017). "Haplotype analysis revealed five blocks across the ABCG2 locus were associated with an increased risk of gout with odds ratios (ORs) from 2.59–3.17 (all P < 0.0001)." (PMID 28855613, 2017). "A consistent finding of GWAS has been the observation that, while SLC2A9 variants are most strongly associated with hyperuricaemia, ABCG2 variants are more strongly associated with gout." (PMID 28566086, 2017). "The genome-wide association studies of serum uric acid identified that ATP-binding cassette transporter, sub-family G, member 2(ABCG2, also known as BCRP) is located in a gout-susceptibility locus on chromosome 4q." (PMID 28630638, 2017). "ABCG2 is one of the transporters involved in uric acid transport in the body and dysfunction of ABCG2 is shown to be related to gout risk." (PMID 28281205, 2017). "Dysfunctional variants of ATP‐binding cassette transporter, sub‐family G, member 2 (ABCG2) causing elevated serum UA levels have been reported to be associated not only with the early onset of gout but also with a later onset of PD." (PMID 28127516, 2017). "In conclusion, this large-scale thorough evaluation of SNPs has identified common genetic variants in ABCG2 that are associated with gout risk." (PMID 28855613, 2017). "Further identification of the functional and causal variant(s) in ABCG2 will lead to a better understanding of the mechanism underlying the development of gout pathologies." (PMID 28855613, 2017).